AR (androgen receptor)
Diseases named in the same sentence as AR in open-access papers (continued):
Sharing a sentence is not in itself a finding about the gene and the disease.
endometrioid tumor (2 papers, 2016 to 2017). A benign, borderline, or malignant epithelial tumor of the female reproductive system characterized by the presence of glands and/or cysts lined by neoplastic cells that resemble endometrial cells. "High BMI, TAV, SAV, VAV and WC, and low LD, were associated with low grade endometrioid tumors and PR and AR positivity (all p≤0.03)." (PMID 29285243, 2017). "In primary tumors the percentage of lesions with AR expression decreased significantly from 74% to 53% from endometrioid grade 1 to grade 3 tumors respectively and further to 41% in non-endometrioid tumors." (PMID 27384477, 2016). "Expression of AR was observed in 93% of hyperplasias, but only in 41% of non-endometrioid tumors." (PMID 27384477, 2016).
endotoxemia (2 papers, 2023 to 2025). "In fact, in a similar model of endotoxemia, one study found that co-treating animals with both α- and β-AR agonists resulted in TNF suppression similar to that in vehicle treated animals, while treating with an α- or β-AR agonist alone increased or decreased TNF, respectively." (PMID 37848937, 2023).
epithelial-myoepithelial carcinoma (2 papers, 2025 to 2026). A malignant neoplasm which occurs mostly in the major salivary glands (most frequently in the parotid gland), but also in the minor salivary glands of the oral mucosa and the tracheobronchial tree. "In addition, one of our cases had transformed into an invasive epithelial-myoepithelial carcinoma with AR-immunopositive luminal tumor cells." (PMID 40033554, 2025). "Histopathology and immunohistochemistry (p63, SMA, CK5/6 positive; PSA, NKX3.1, and AR negative, with downregulated PSMA-expression) established the diagnosis of low-grade epithelial-myoepithelial carcinoma of the trachea." (PMID 41897615, 2026).
female infertility (2 papers, 2018 to 2025). Diminished or absent ability of a female to achieve conception. "Mice lacking FKBP52 displayed female infertility and several defects in male sexual development, which is in line with the role of FKBP52 in hormone signaling, especially as an PR and androgen receptor (AR) regulator." (PMID 30568592, 2018).
fetal growth restriction (2 papers, 2021 to 2022). A fetus that does not grow beyond the 10th percentile of conventionally accepted weight for gestational age. "In 12-months-old females with intrauterine growth restriction, increased values of plasma testosterone and blood pressure were observed, and blockade of the androgen receptor decreased blood pressure." (PMID 35270026, 2022). "Moreover, enalapril (an angiotensin-converting enzyme inhibitor) suppressed the increase of blood pressure in a intrauterine growth restriction female, however this was less significant if the androgen receptor was blocked." (PMID 35270026, 2022).
Genetic neuromuscular disease (2 papers, 2022 to 2023). "Spinal and bulbar muscular atrophy (SBMA) is a neurodegenerative and neuromuscular genetic disease caused by the expansion of a polyglutamine-encoding CAG tract in the androgen receptor (AR) gene." (PMID 36277484, 2022).
granulosa cell tumor (2 papers, 2014 to 2025). A slow-growing, malignant tumor, characterize by the presence of granulosa-like cells and Call-Exner bodies, that is almost always found in the ovary. "In addition, DNA replication error, on analysis of the lengths of CAG repeats in androgen receptor gene, revealed defective DNA mismatch repair system in the granulosa cell tumor." (PMID 25297715, 2014).
hearing loss (2 papers, 2018 to 2021). "Androgen receptor inhibition protects against cochlear injuries in KM-induced hearing loss rats by attenuating megalin expression, revealing anti-inflammatory and anti-apoptotic effects." (PMID 34070066, 2021).
Hepatitis (2 papers, 2021 to 2025). Inflammation of the liver. "Although HCC progression was phenotypically suppressed in SHBG mice compared with that in WT mice, which is similar to our published data, EE2 could expose SHBG mice to HCC risk by triggering markedly pronounced hepatitis, fibrosis, and compensatory proliferation with AR activation." (PMID 34830439, 2021).
hyperlipidaemia (2 papers, 2022). "Flutamide is a common AR antagonist used to treat conditions associated with PCOS, such as hirsutism, anovulation and hyperlipidaemia." (PMID 35885010, 2022). "Future studies will be needed to verify the proposed mechanism by which AR-9 exerts anti-hyperlipidemia effects in the present study." (PMID 36176455, 2022). "Similarly, metabolic abnormalities, including constraints on adipocyte maturation, diminished adipocyte release of adiponectin, increased intra-abdominal fat storage and hyperlipidaemia, are observed in a normal-weight PCOS patients with elevated androgen and AR expression." (PMID 35885010, 2022).
Hyperoxaluria (2 papers, 2019 to 2023). Increased excretion of oxalates in the urine. "However, they found that AR increase miRNA expression which inhibit CSF-1 resulting in M2 macrophages inhibition and promoting hyperoxaluria." (PMID 37093310, 2023).
hypertrophic cardiomyopathy (2 papers, 2008 to 2023). A condition in which the myocardium is hypertrophied without an obvious cause. "Also, a recent study of patients with hypertrophic cardiomyopathy demonstrated polymorphisms in the estrogen receptor alpha (ESR1) gene, as well as in the androgen receptor (AR) gene to be associated with left ventricular wall thickness in men, but not in women." (PMID 19077249, 2008).
hypomyelinating leukodystrophy (2 papers, 2023 to 2024). "AR mutations in PI4KA cause a variable phenotypical spectrum ranging from severe neurodevelopmental disorder with spasticity, hypomyelinating leukodystrophy, and brain abnormalities (NEDSPL) to pure spastic paraplegia type 84 (SPG84)." (PMID 38003592, 2023).
influenza (2 papers, 2020 to 2021). An acute viral infection of the respiratory tract, occurring in isolated cases, in epidemics, or in pandemics; it is caused by serologically different strains of viruses (influenzaviruses) designated A, B, and C, has a 3-day incubation period, and usually lasts for 3 to 10 days. "In whole blood of CAP patients mean AR pathway activity was increased, compared to healthy individuals or patients with an influenza infection, while around one third of CAP patients had AR pathway activity in the normal range." (PMID 34888328, 2021).
Inguinal hernia (2 papers, 2014 to 2018). Protrusion of the contents of the abdominal cavity through the inguinal canal. "Mutations in the androgen receptor that causes androgen insensitivity have been previously associated with inguinal hernia." (PMID 29382056, 2018). "Interestingly, this region (53,940,129 bp–115,135,321 bp) on chromosome X harbors the Androgen Receptor gene (AR; chrX:60,314,522 bp–60,504,529 bp Sscrofa10.2), which is a great candidate gene for the inguinal hernias, trait that is under our study." (PMID 29382056, 2018). "Newborn girlswith an inguinal hernia, most probably have CAISand should undergo a prompt karyotype analysis.CAIS is inherited in an X-linked recessive mannerand characterized by resistance to androgen due toa mutation in the AR gene." (PMID 24520507, 2014).
insomnia (2 papers, 2022 to 2024). A sleep disorder characterized by difficulty in falling asleep and/or remaining asleep. "We also observed trait-specific patterns of such sequence class enrichment, such as ‘CEBPB-binding site’ (Insomnia: OR = 5.25, p = 0.01) and ‘FOXA1/AR/ESR1-binding site’ (intelligence: OR = 4.69, p = 0.01)." (PMID 38639992, 2024).
Kaposi's sarcoma (2 papers, 2024 to 2025). A malignant neoplasm characterized by a vascular proliferation which usually contains blunt endothelial cells. "This study aims to examine the expression of androgen receptor (AR) and estrogen receptor (ER) in patients with classic Kaposi's sarcoma (CKS) in Xinjiang, as well as to assess the serum levels of sex hormones in these patients." (PMID 39349354, 2024).
laryngeal carcinoma (2 papers, 2011 to 2022). Carcinoma that arises from the laryngeal epithelium. "Further investigation is needed to evaluate AR and the molecular pathways of cancer that can activate it, as potential molecular targets for laryngeal carcinoma therapy." (PMID 22191056, 2011). "Higher expression of AR contributes to the proliferation of cells in different HNC types, including laryngeal carcinoma and juvenile nasopharyngeal fibroma." (PMID 35517428, 2022). "A reverse correlation between nuclear AR and cytoplasmic ILK expression was evidenced, indicating an interaction of those molecules in laryngeal carcinoma." (PMID 22191056, 2011). "Additionally, in the current study we show a correlation of low expression of AR in tumors with ILK cytoplasmic overexpression (r = −0.260, P = 0.01) which possibly suggests an interaction of those molecules in laryngeal cancer, yet not in line with the hypothesis of ARs being activated by ILK." (PMID 22191056, 2011).
lipid metabolic disorders (2 papers, 2023). "There is evidence that the acquired metabolic phenotype associated with androgen receptor (AR)-targeted therapies is related to glucose and lipid metabolism disorders." (PMID 37070095, 2023). "This review will help in extracting multiple new receptors and proteins as targets for drug therapy as well as help in better understanding AR as a target against lipid metabolic disorders in neurodegenerative diseases." (PMID 41340464, 2023). "Also, studies on neural lipid metabolic disorders have shown that testosterone can activate AR and show evidence of a potential neuroprotective role in AD." (PMID 41340464, 2023).
liver neoplasm (2 papers, 2010 to 2019). Tumors or cancers of the LIVER. "AR is expressed in the liver of rats and humans, and hepatic tumor development is likely influenced by androgens, as indicated by the fact that males have a greater prevalence of liver neoplasms in humans and rodents." (PMID 20368123, 2010).
Lobular carcinoma (2 papers, 2017 to 2026). "MUCL1 was expressed in 25% of cases in our cohort, enriched in apocrine and lobular carcinomas, and strongly correlated with AR, FOXA1, and GCDFP-15." (PMID 41987297, 2026).
long QT syndrome (2 papers, 2023 to 2024). "Androgen receptor antagonists are linked to an increased risk of long QT syndrome, torsades de pointes, and sudden cardiac death." (PMID 37273124, 2023).
lung disease (2 papers, 2020). "Smoking is a known risk factor for lung disease and a more severe COVID-19 disease course; therefore, we examined whether smoking status could alter the expression level of AR and ACE2 in male and female lungs." (PMID 33310900, 2020). "Previous studies have reported that exposure to cigarette smoke results in a higher likeliness of suffering from lung disorders with an up-regulated expression of AR contributing to a series of downstream pathological changes." (PMID 32493296, 2020).
lung squamous cell carcinoma (2 papers, 2018 to 2023). "Whether NSCLC is a sex hormone-related tumor is still controversial, the cancer genome atlas (TCGA) has identified androgen receptor (AR) to be mutated, deleted and amplified across human lung squamous cell carcinoma." (PMID 37716981, 2023).
microcephaly (2 papers, 2018 to 2025). A congenital or acquired developmental disorder in which the circumference of the head is smaller than normal for the person's age and sex. "Dysregulation of AR pathway may result in microcephaly or atrophy in the cerebral and cerebellar cortex, which have been observed in some human patients affected by ZMIZ1 syndrome." (PMID 40529245, 2025).
migraine (2 papers, 2022 to 2023). "AR is an androgen receptor gene; animal experiments have demonstrated that androgen levels are actively related to migraine risk." (PMID 36479181, 2022). "Within the scope of literature that examines androgen receptor activity on central trigeminal neurotransmission, clinical proposals on the impact of testosterone within migraine pathology have mainly investigated the association between androgens and observations in headache pain relief." (PMID 37795389, 2023). "Such active ingredients may influence neuroactive ligand-receptor interaction, calcium signaling pathways, signaling pathways in cancer, cAMP signaling pathways, and PI3K pathways by acting on multiple targets such as PTGS2, PIK3CA, PIK3CB, PIK3CD, F2, and AR to treat migraine." (PMID 36479181, 2022).
mucinous carcinoma (2 papers, 2022). "In the present study, mucinous carcinomas in older patients were mostly positive for both GCDFP-15 and AR and showed abundant eosinophilic cytoplasm or apocrine snouts, suggesting their apocrine-like characteristics." (PMID 36553136, 2022). "Interestingly, the type A mucinous carcinomas of older individuals also exhibited apocrine-like immunohistochemical characteristics (GCDFP-15 positivity and AR positivity)." (PMID 36553136, 2022). "We conclude that the biologically essential features of mucinous carcinomas in older patients are apocrine-like immunohistochemical features (GCDFP-15/AR positivity), rather than neuroendocrine features." (PMID 36553136, 2022).
mucoepidermoid carcinoma (2 papers, 2023). A carcinoma morphologically characterized the presence of cuboidal mucous cells, goblet-like mucous cells, squamoid cells, cystic changes, and a fibrotic stromal formation. "Mucoepidermoid carcinoma (MEC) had AR and HER2 positivity rates of 17% and 20%, respectively, while for ACC it was even lower." (PMID 37799960, 2023). "The mucoepidermoid carcinoma of the breast was weakly estrogen receptor and androgen receptor positive and progesterone receptor negative, but exceptionally showed human epidermal growth factor receptor 2 gene amplification." (PMID 38062474, 2023).
muscle disorder (2 papers, 2017 to 2022). "Additionally, AR (androgen receptor) was found to connect cancers and muscular diseases as an inter-gene." (PMID 28295050, 2017).
myelolipoma (2 papers, 2014 to 2024). "Our data indicated that MC2R and/or AR were involved in the pathogenesis of myelolipomas associated with CAH, suggesting a stimulatory hormonal effect as a trigger for tumor growth." (PMID 24884994, 2014). "AR expression was previously assessed in a single case of bilateral myelolipoma associated with CAH using a semi-quantitative technique, but the results were negative." (PMID 24884994, 2014). "In conclusion, we first demonstrated here MC2R or AR overexpression in giant bilateral myelolipomas from poor-compliance CAH patients." (PMID 24884994, 2014). "AR overexpression was detected in 2 tumors: a giant bilateral myelolipoma in a CAH patient and a sporadic case." (PMID 24884994, 2014). "In the current study, AR overexpression was detected in 2 tumors: a giant bilateral myelolipoma in a CAH patient and a sporadic case." (PMID 24884994, 2014). "However, considering the high frequency of association between giant bilateral myelolipomas and CAH, we hypothesized that ACTH and AR might have a role in the pathogenesis of myelolipomas." (PMID 24884994, 2014). "ACTH likely plays a role in myelolipoma formation; however, we found a decreased expression of the ACTH receptor (MC2R) and androgen receptor (AR) in myelolipoma tissue, and an increased expression in CAH adrenal tissue." (PMID 38473790, 2024). "In this study, we analyzed MC2R and AR expression as well as nCAG AR repeat numbers in two bilateral giant myelolipomas from CAH patients and two unilateral sporadic myelolipomas." (PMID 24884994, 2014). "Indeed, MC2R and androgen receptor (AR) expression was previously evaluated in a single case of giant bilateral myelolipoma in a CAH patient and was negative using a semi-quantitative approach." (PMID 24884994, 2014).
myopia (2 papers, 2023 to 2025). "Additionally, we identified 4 significant DEGs of myopia: KIAA1211, CALR3, DNASE2B, and CCDC178, and 2 common targets: AR and TYRO3 among DZP, myopia, DEG analysis, and WGCNA." (PMID 37747014, 2023).
neurofibroma (2 papers, 2008 to 2019). An intraneural or extraneural neoplasm arising from nerve tissues and neural sheaths. "The functions of oestrogen receptor and progesterone receptor have been reported; however, the contribution of AR in neurofibroma progression needs further clarification." (PMID 31852972, 2019). "They reported differential expression of ER, PR, and androgen receptor in primary neurofibromas and neurofibroma-derived Schwann cells, as compared to unaffected Schwann cells." (PMID 21876657, 2008).
non-alcoholic fatty liver disease (2 papers, 2022). "Specifically, diacylglycerols (DAGs) were shown to activate AKT which then in turn would activate AR demonstrating a further linkage between the AKT/mTOR pathway and AR in non-alcoholic fatty liver disease-mediated HCC." (PMID 36430245, 2022).
non-Hodgkin lymphoma (2 papers, 2019 to 2024). Distinct from Hodgkin lymphoma both morphologically and biologically, non-Hodgkin lymphoma (NHL) is characterized by the absence of Reed-Sternberg cells, can occur at any age, and usually presents as a localized or generalized lymphadenopathy associated with fever and weight loss. "ABBV-075 is a novel BET inhibitor that triggers apoptosis in AML cells, non-Hodgkin lymphoma, and MM cells, whereas ABBV-744 selectively targets the BD2 domain, displaces BRD4 from androgen receptor (AR)-containing super-enhancers, and inhibits AR-dependent transcription." (PMID 38225241, 2024).
oropharyngeal squamous cell carcinoma (2 papers, 2022 to 2025). "In another study, AR expression was detected in tumor samples from oropharyngeal squamous cell carcinoma (OPSCC) patients." (PMID 35517428, 2022). "AR shows positive expression in HNCs, including oropharyngeal squamous cell carcinoma and salivary gland tumors." (PMID 35517428, 2022).
osteoarthritis (2 papers, 2018 to 2024). A noninflammatory degenerative joint disease occurring chiefly in older persons, characterized by degeneration of the articular cartilage, hypertrophy of bone at the margins and changes in the synovial membrane. "Additionally, study have suggested an association between androgen receptor polymorphism and osteoarthritis, and recent Mendelian randomization studies have further indicated a causal relationship between androgen and the occurrence of osteoarthritis." (PMID 38632649, 2024). "Furthermore, published literature documented that AR has anti-inflammatory activity and is one of the commonly used herbs for the management of painful osteoarthritis." (PMID 30405409, 2018).
Osteopenia (2 papers, 2023 to 2024). Osteopenia is a term to define bone density that is not normal but also not as low as osteoporosis. "This study shows that AR-mediated effects are vital for healthy skeletal development and may indicate that androgen therapy may benefit patients at risk of osteopenia." (PMID 36596999, 2023).
ovarian teratoma (2 papers, 2021 to 2022). A non-seminomatous germ cell tumor arising from the ovary. "Unstained histology sections of the ovarian teratoma containing prostatic tissue were evaluated using immunohistochemistry for PSA and androgen receptor." (PMID 34618214, 2022).
pancreatic ductal adenocarcinoma (2 papers, 2020 to 2021). An infiltrating adenocarcinoma that arises from the epithelial cells of the pancreas. "LEF1 and AR were also expressed in majority of SPNs, while pancreatic ductal adenocarcinomas and pan NETs showed no expression." (PMID 33298094, 2020).
parasitemia (2 papers, 2021 to 2023). "Previous reports have shown that AR has a relevant role in the immune response derived from parasitic infections." (PMID 34668739, 2021).
Parkinson’s (2 papers, 2018 to 2023). "Thus, the AR-mediated metabolic pathway is evident in the case of Parkinson’s." (PMID 41340464, 2023).